ZEB1 (zinc finger E-box binding homeobox 1)
Diseases named in the same sentence as ZEB1 in open-access papers (continued):
Sharing a sentence is not in itself a finding about the gene and the disease.
gastric cancer (continued). "Collectively, these data demonstrated that indisulam inhibited the migration of gastric cancer cells by degrading ZEB1 through DCAF15." (PMID 36805336, 2023). "Scratch assay and small RNA interference reveal that ZEB1 is critical for the inhibitory effect of indisulam on the migration of gastric cancer cells." (PMID 36805336, 2023). "For example, lncRNA PCAT-1 is overexpressed in cisplatin-resistant gastric cancer tissues and cells, where it promotes resistance to cisplatin by affecting the miR-128/ZEB1 axis." (PMID 35089117, 2022). "Recently, LINC01559 was found to recruit IGF2BP2 to stabilize ZEB1 expression and accelerate gastric cancer cell proliferation, migration and EMT." (PMID 35299748, 2022). "PRTG activates the cGMP/PKG signaling pathway downstream of gastric cancer cells in response to the induction of the epithelial-mesenchymal transition (EMT) transcription factor ZEB1, which has an important role in the progression of gastric cancer." (PMID 36292752, 2022). "Mir-1290 in gastric cancer-derived exosomes can inhibit T cell proliferation through the grainyhead-like 2 (Grhl2)/zinc finger E-box binding homeobox 1 (ZEB1)/PD-L1 axis and participate in immune tolerance." (PMID 36341377, 2022). "We particularly identified the dual treatment-selective downregulation of ZEB1 expression, which was critical for gastric cancer cell proliferation." (PMID 34302038, 2021). "Next, we further confirmed that overexpression of ZEB1 significantly enhanced the expression of PRTG in gastric cancer cells." (PMID 33542225, 2021). "Overall, our results suggest that ZEB1-mediated transcription of PRTG is critical to the activation of cGMP/PKG signaling pathway induced by H. pylori infection in gastric cancer." (PMID 33542225, 2021). "Next, the expression of ZEB1 in response to H. pylori infection in gastric cancer cells was then evaluated by western blot and qRT-PCR analysis." (PMID 33542225, 2021). "For example, the widely studied tumor suppressor Fbxw7 induced the Snail ubiquitination and degradation in non-small cell lung cancer 14, controlled the RhoA protein level and the downstream Snail or Zeb1 expression in gastric cancer." (PMID 33531987, 2021). "ITGB3 and ZEB1 were found to be targeted by miR-124-3p in promoting gastric cancer proliferation and invasion." (PMID 33482814, 2021). "Particularly, in gastric cancer cells, miR-141/200a diminishes the invasion and migration of tumor cells via suppressing ZEB1." (PMID 32664703, 2020). "In gastric cancer cells, expression of miR-203 undergoes down-regulation, resulting in an up-regulation of ZEB1 and resistance of cancer cells to radiotherapy." (PMID 32664703, 2020). "SMAD3 induced ECAD in a gastric cancer cell line following transcriptional induction of the miR-200b/a promoter and subsequent inhibition of ZEB1 expression." (PMID 33260366, 2020). "In gastric cancer cells, PCAT-1 induces the resistance of cancer cells into cisplatin therapy by stimulation of ZEB1 through miR-128 inhibition, leading to the enhanced progression and malignancy of gastric cancer cells." (PMID 32664703, 2020). "Circular RNA Circ-PVT1 reverses this axis by sponging miR-124-3p and elevating the expression of ZEB1 to induce PTX resistance in gastric cancer cells." (PMID 32664703, 2020). "In gastric cancer patients, increased expression of ZEB-1 was markedly correlated with peritoneal dissemination and worse clinical prognosis." (PMID 31248382, 2019). "The present study validated the prognostic value and clinicopathological association of ZEB1 and ZEB2 in digestive cancers, especially in gastric cancer." (PMID 28416756, 2017). "We only performed secondary analyses in gastric cancer, because only in gastric cancer did both ZEB1 and ZEB2 have significant prognostic value, and studies concerning gastric cancer provided adequate data for secondary analyses." (PMID 28416756, 2017).
gastric cancer (continued). "A study of EBV-mediated gastric carcinoma uncovered an increase in zeb1 when an EBV-minus gastric cancer cell line was transfected with EBERs." (PMID 26121143, 2015). "The present study investigated the function of miR-141 in gastric cancer cell migration, and evaluated the contribution of zinc finger E-box-binding homeobox 1 and 2 (ZEB1/2) in miR-141 mediated migration of gastric cancer cells." (PMID 25975736, 2015). "In comparison with other EMT markers including Snail-1 and vimentin, aberrant expression of ZEB1 is more common in gastric cancers." (PMID 25197668, 2014). "ZEB1 expression level was correlated with the mesenchymal phenotype displayed by the gastric cancer." (PMID 25197668, 2014). "CD44 expression was correlated with ZEB1 expression and was inversely correlated with the E-cadherin levels in the gastric cancer." (PMID 25197668, 2014). "In gastric carcinoma, ZEB1 expression is correlated with metastasis, corroborating its relevance in gastric cancer progression." (PMID 23565224, 2013). "High ZEB1 expression has been indicated to promote tumor growth in gastric cancer." (PMID 40092690, 2025). "ZEB1 expression is significantly higher in gastric carcinoma tissue than in adjacent normal mucosa." (PMID 40092690, 2025). "Since our cell line–based experiments discovered that indisulam directly modulated ZEB1, we analyzed the expression level of ZEB1 instead of N-cadherin and DCAF15 in gastric cancer tissues to further explore the role of ZEB1 in the progression of gastric cancer." (PMID 36805336, 2023). "In addition, our cell line–based experiments demonstrate that indisulam inhibits the migration of gastric cancer cells in a ZEB1-dependent manner." (PMID 36805336, 2023). "However, indisulam enhances the interaction between DCAF15 and ZEB1 and thus significantly enhanced the ubiquitination and subsequent degradation of ZEB1 in gastric cancer cells." (PMID 36805336, 2023). "Moreover, analysis of the gastric datasets in Oncomine disclosed that ZEB1 mRNA was expressed significantly higher in gastric cancer tissues than in normal gastric mucosa." (PMID 36805336, 2023). "A role for circPVT1 in metastasis was also found in PAC resistant gastric cancer models where via sponging miR-124-3p it increased expression of the transcription factor zinc finger E-box binding homeobox (ZEB1), which negatively regulates E-cadherin thus promoting cell migration." (PMID 36434179, 2023). "We continued the qRT-PCR analysis of the samples, and among the EMT-related markers, the expression levels of mesenchymal markers CDH2 and ZEB1 genes were significantly reduced in gastric cancer cells after TGFβ gene silencing, while CDH1 expression was not significantly altered." (PMID 36119489, 2022). "Moreover, Circular RNA circ-PVT1 upregulated ZEB1 expression by sponging miR-124-3p and enhanced paclitaxel resistance of gastric tumor and gastric cancer cells." (PMID 33482814, 2021). "Therefore, we suggested that Fbxo21 inhibited the EMT in gastric cancer by downregulating Snail and Zeb1, two upstream transcription factors of the EMT." (PMID 33531987, 2021). "In addition, ZEB1 positively associated PRTG expression and increased in gastric cancer tissues, as well as predicted poor prognosis of gastric cancer patients." (PMID 33542225, 2021). "Therefore, β-elemene can reverse EMT in MDR gastric cancer cells by inhibiting the transcription factors ZEB1 and ZEB2 and through the miR-1323/Cbl-b/EGFR pathway." (PMID 34641334, 2021). "In addition, exosomes in gastric cancer downregulate Cbl-b and E-cadherin and upregulate Zincfinger Ebox Binding Homeobox 1 (ZEB-1), ZEB-2, and vimentin in a concentration-dependent manner." (PMID 34641334, 2021). "Indeed, H. pylori infection and ZEB1 overexpression activated cGMP/PKG pathway in gastric cancer cells, and which can be blocked by the PRTG silencing." (PMID 33542225, 2021). "MiR-124-3p suppresses ZEB1 to sensitize gastric cancer cells into PTX therapy." (PMID 32664703, 2020).
gastric cancer (continued). "Additionally, this study provides a clue about the functional interaction between ZEB1 and AR signaling pathways in gastric cancer." (PMID 32153739, 2020). "In addition, exogenous expression of tumor suppressor miR-200c has been found to sensitize gastric cancer cells to trastuzumab by targeting and downregulating ZEB1 and ZEB2." (PMID 32192494, 2020). "Here, we hypothesized that CASC15‐miR‐33a‐5p‐CDKN1A/ZEB1 axis would be a novel pathway in gastric cancer." (PMID 29489064, 2018). "In addition to that, another 1 previous excluded non-cohort study was retrieved because it reported the relationship between ZEB1 expression in gastric cancer tissues and clinicopathological characteristics." (PMID 28416756, 2017). "Furthermore, high ZEB1 expression was an independent indicator of peritoneal dissemination, which was responsible for the majority of mortality in gastric cancer patients." (PMID 28416756, 2017). "In summary, this work demonstrated that indisulam inhibits the migration of gastric cancer cells through degrading the transcription factor ZEB1 and regulating the downstream EMT process, suggesting that indisulam may exhibit antimetastatic activity in gastric cancer." (PMID 36805336, 2023). "Furthermore, we discovered that 1,25(OH)2D treatment increased the expression of tumor necrosis factor alpha-induced protein 3 (TNFAIP3), which is required for the ubiquitination and degradation of EMT transcription factors like SNAIL1/2 and ZEB1 in gastric cancers." (PMID 37228489, 2023). "Therefore, we next asked whether indisulam inhibits the migration of gastric cancer cells by downregulating ZEB1." (PMID 36805336, 2023). "TAZ and zinc-finger E-box binding homeobox 1 (ZEB1), a transcription factor closely associated with EMT, were co-overexpressed in cells with a mesenchymal phenotype in vitro, in areas of hyperplasia in H. pylori-infected patients, as well as at the invasive front of gastric carcinoma." (PMID 36635265, 2023). "PCAT-1 confers DDP resistance in gastric cancer (GC) cells through the miR-128/ZEB1 axis, providing a promising therapeutic strategy for GC." (PMID 33980216, 2021). "In gastric cancer (GC), circPVT1 contributed to paclitaxel resistance of GC cells through regulating ZEB1 expression by sponging to miR-124-3p." (PMID 34312371, 2021). "In addition, circRNA circ-PVT1 could facilitate paclitaxel (PTX) resistance of gastric cancer cells via up-regulating ZEB1 mediated by miR-124-3p." (PMID 32192494, 2020). "Besides, lncRNA CASC15 was found to promote EMT in gastric cancer by targeting ZEB1." (PMID 33292221, 2020). "To confirm these results in vivo, we evaluated TAZ and ZEB1 expression and subcellular localization by immunohistochemistry on serial tissue sections of gastric mucosa from uninfected and H. pylori-infected mice and patients, as well as human gastric carcinoma." (PMID 32545795, 2020). "And the CHIP assay in gastric cancer cells showed that ZEB1 could bind on IRF6 promoter." (PMID 31019894, 2019). "Additionally, the result of CHIP assay showed that ZEB1 could directly bind on the IRF6 promoters in gastric cancer cells." (PMID 31019894, 2019). "Importantly, circ-PVT1 could bind to miR-124-3p as a miRNA sponge to up-regulate ZEB1 expression, thereby expediting paclitaxel resistance of gastric cancer cells." (PMID 31793989, 2019). "More in depth studies on ZEB1 expression and the development of gastric cancer found that in addition to affecting invasion and metastasis the overexpression of ZEB1 may actually be related to its development and occurrence when comparing gastric carcinoma to normal gastric mucosa tissues." (PMID 32309604, 2018). "In gastric cancer (GC), lncRNA MAGI2-AS3 promotes ZEB1 expression and EMT by sponging miR-141/200a, thus facilitating cellular migration and invasion." (PMID 39937018, 2025). "Various studies have shown that ZEB1 has an oncogenic role and functions as an EMT regulator in gastric cancers." (PMID 40092690, 2025).
gastric cancer (continued). "CASC15 promotes EMT, and CASC15 overexpression is closely related to gastric cancer invasion and metastasis by regulating the CASC15/miR-33a-5p/ZEB1 pathway." (PMID 40191723, 2025). "Studies have shown that proteins such as: Snail-1, β-catenin, E-cadherin, vimentin, ZEB-1, and CD44 markers are EMT-interrelated in gastric cancer." (PMID 37609398, 2023). "GSA revealed that VIP and ZEB1 had activating effects on EMT and inhibitory effects on the cell cycle pathway in both colon and gastric cancers." (PMID 37444395, 2023). "Taken together, we discovered a new substrate ZEB1 for DCAF15 induced by the molecule glue indisulam and elucidated the molecular mechanism by which indisulam regulates the migration of gastric cancer cells." (PMID 36805336, 2023). "The results of this study showed that TGFβ1, TGFβ2 and TGFβ3 were positively correlated with EMT, CDH2, VIM and ZEB1 and significantly negatively correlated with CDH1 in multiple gastric cancer datasets." (PMID 36119489, 2022). "In multiple gastric cancer datasets, TGFβ were positively correlated with EMT score and mesenchymal markers (CDH2, VIM and ZEB1), while significantly negatively correlated with epithelial marker CDH1." (PMID 36119489, 2022). "In gastric cancer, for example, circ-PVT1 is upregulated and sequesters miR-124-3p, thereby upregulating ZEB1 expression and promoting tumor cell resistance to paclitaxel treatment." (PMID 35974419, 2022). "LRP4 is overexpressed in papillary thyroid and gastric cancers, where it promotes EMT through PI3K/AKT pathwayand modulation of N-cadherin, ZEB1 and EZH2." (PMID 36012187, 2022). "We have previously shown that miR-200c targets VEGFR and MMP9 in gastric cancer cell lines and miR-200c inhibits CXCR4 indirectly by targeting ZEB1." (PMID 33673143, 2021). "Taken together, our findings suggested that H. pylori infection depends on ZEB1 to induce PRTG upregulation, and which leading to the development and progression of gastric cancer through activating cGMP/PKG signaling pathway." (PMID 33542225, 2021). "The expression levels of TGFB1, TGFB2, ZEB1 and PTBP1 were detected by qRT-PCR in 92 pairs of gastric carcinoma specimens and adjacent normal tissues (Cohort 2)." (PMID 34706749, 2021). "On the other hand, overexpression of MAGI2-AS3 has been explained to promote tumor progression by absorbing miR-141/200a and consequently, up-regulating ZEB1 which is an EMT promoting transcription factor, in gastric cancer cells." (PMID 32727450, 2020). "Since it has been shown that AR overexpresses in Gastric Cancer (GC) as a male-predominant tumor, the goal of this study was to evaluate whether AR could regulate ZEB1 expression in GC." (PMID 32153739, 2020). "In human gastric carcinoma, nuclear TAZ and ZEB1 were strongly upregulated compared to healthy gastric mucosa." (PMID 32545795, 2020). "Recent works suggest that lncRNA-ATB functions as ceRNA also for miR-141-3p, a direct binder and inhibitor of ZEB1 and ZEB2, in breast and gastric cancer and that its expression correlates to trastuzumab resistance in HER2-positive breast cancer cells." (PMID 31003545, 2019). "We found a decreased expression of the epithelial markers CDH1, EpCAM, and increased expression of the mesenchymal markers CDH2, Vimentin, ZEB1, Snail, MMP14 and Twist in un-captured cells in gastric cancer cell lines AGS, SGC7901 and BGC-823." (PMID 27654478, 2016). "Then, we detected the expression of transcriptional factors, such as snail, twist, ZEB1 and ZEB2 in gastric cancer cells using real-time PCR." (PMID 27102302, 2016). "Forced expression of miR-141 significantly reduced ZEB1/2 mRNA and protein expression levels in both HGC-27 and SGC-7901 gastric cancer cells." (PMID 25975736, 2015). "ZEB1 gene expression was previously found to be greater in gastric cancer tissues compared to nearby non-tumor or normal gastric tissues." (PMID 40693059, 2025).
gastric cancer (continued). "Furthermore, zinc finger E-box-binding homeobox 1 (ZEB1), ZEB2, and Snail are among the EMT-related proteins that show increased expression in gastric cancer tissues." (PMID 41188920, 2025). "In addition, it was clarified that epidermal growth factor (EGF) induced the upregulation of ZEB1 and ZEB2 via the Akt signaling pathway in gastric carcinoma, which was consistent with the results of our research." (PMID 40510028, 2025). "Our putative MAGI2-AS3/miR-33b-5p/ZEB1 triplet was not described, while the activating effect of MAGI2-AS3 on ZEB1 via miR-141/200a has been previously shown in gastric cancer." (PMID 39519394, 2024). "In addition, gastric cancer samples from 14 patients (25%) presented with a transcriptomic profile (low levels of CDH1; high levels of ZEB1) consistent with the presence of an EMT (Epithelial-to-Mesenchymal-Transition) phenotype." (PMID 39323992, 2024). "Similarly, LINC01559 can enhance the stability of ZEB1 mRNA by recruiting IGF2BP2, accelerate the proliferation and migration of gastric cancer cells, and promote the malignant development of gastric cancer." (PMID 38040698, 2023). "Notably, IGF2BP2 has been found to target SIRT1, ZEB1, and HMGA1, thereby promoting gastric cancer growth and metastasis." (PMID 37865637, 2023). "Additionally, in gastric cancer, VIP and ZEB1 showed inhibitory effects on the apoptosis pathway (FDR < 0.05)." (PMID 37444395, 2023). "Moreover, the inhibitory effects on the apoptosis pathway observed in gastric cancer suggest potential roles for VIP and ZEB1 in modulating cell survival mechanisms in this specific cancer type." (PMID 37444395, 2023). "For example, lncRNA PCAT-1, which is significantly expressed in tissues and cells of gastric cancer resistant to DDP, increases DDP resistance in gastric cancer cells by engaging EZH2 to epigenetically repress PTEN expression and controlling the miR-128/ZEB1 axis." (PMID 38162289, 2023). "ZEB1 accumulation enhanced the invasion and EMT of liver and gastric cancer cells." (PMID 36248798, 2022). "Gastric cancer (GC) cell-derived exosomes contain miR-1290, which suppresses T cell activation by targeting the grainyhead-like 2 (GRHL2)/zinc finger E-box binding homeobox 1 (ZEB1) pathway, thereby provoking immune escape." (PMID 35562884, 2022). "Interrogation of CCLE database revealed that FZD5 is positively correlated with epithelial-related factors CDH1 (E-cadherin), OCLN (Occludin), EPCAM and ELF3, while negatively correlated with mesenchymal-related factors VIM (Vimentin), SNAI2 (Slug), ZEB1 and ZEB2 in 37 gastric cancer cell lines." (PMID 33618713, 2021). "Given that CHFR is highly methylated and silenced in G2/M phase in gastric cancer, it is speculated that CHFR is an E3 ubiquitin ligase for ZEB1 and exerts its tumor suppression through destabilizing ZEB1 in TNBC." (PMID 34462429, 2021). "Additionally, it was reported that miR-5590-3p inhibited tumour growth in gastric cancer by targeting DDX5, and repressed diffuse large B cell lymphoma progression and immune evasion through targeting ZEB1 to regulate PD-1/PD-L1 checkpoint." (PMID 33088216, 2020). "For instance, lncRNA PCAT-1, a highly expressed lncRNA in DDP-resistant gastric cancer tissues and cells, promotes DDP resistance of gastric cancer cells via epigenetically suppressing PTEN expression by recruiting EZH2, as well as regulating the miR-128/ZEB1 axis." (PMID 32192494, 2020). "We previously reported that ZEB1 and other EMT markers were upregulated during this sequence of pre-neoplastic lesions induced by H. pylori in mice and humans; they remained upregulated in human gastric carcinoma." (PMID 32545795, 2020). "In gastric carcinoma, miR-381 inhibits Sox4, TMEM16A, and ZEB1 and suppresses metastasis." (PMID 33324542, 2020).